JCAD (junctional cadherin 5 associated)
Synonyms: KIAA1462
Tractability: No criterion of Open Targets' tractability assessment is met for any kind of drug.
Gene: Protein-coding gene on chromosome 10 (30,012,803 to 30,115,494, reverse strand). Ensembl gene ENSG00000165757.
Subcellular location: Cell junction, adherens junction
Subcellular location (Human Protein Atlas): Cell Junctions; Vesicles
Gene Ontology:
Biological process: positive regulation of blood vessel endothelial cell proliferation involved in sprouting angiogenesis; positive regulation of cell migration involved in sprouting angiogenesis; positive regulation of MAPK cascade; positive regulation of vascular endothelial growth factor signaling pathway; positive regulation of sprouting angiogenesis
Cellular component: adherens junction; perinuclear region of cytoplasm; ruffle membrane; cell junction; cell-cell junction
Genetic constraint (gnomAD): Loss-of-function variants: 39 observed, 102.69 expected, observed/expected ratio (o/e) 0.38, 90% interval 0.29 to 0.5. The upper end of that interval is the gene's LOEUF score, 0.5, which puts it in group 2 of 6, group 1 being the genes least tolerant of losing a copy. Missense variants: 1,698 observed, 1,823.6 expected, observed/expected ratio (o/e) 0.93, 90% interval 0.89 to 0.97. Synonymous variants: 690 observed, 719.74 expected, observed/expected ratio (o/e) 0.96, 90% interval 0.9 to 1.02.
Homologues: Orthologues: chimpanzee JCAD (99% identical), macaque JCAD (94% identical), guinea pig JCAD (63% identical), pig JCAD (59% identical), rat Jcad (53% identical), mouse Jcad (53% identical), rabbit JCAD (53% identical), tropical clawed frog jcad (30% identical).
Diseases named in the same sentence as JCAD in open-access papers:
JCAD is named in the same sentence as 34 diseases in open-access papers, as found by Europe PMC text mining. Sharing a sentence is not in itself a finding about the gene and the disease. The quoted sentences say what the papers report.
coronary artery disease (13 papers, 2013 to 2025). "The JCAD (junctional cadherin 5 associated; formerly KIAA1462) locus has been implicated in coronary artery disease through genome-wide association studies, but data in diabetic populations are scarce." (PMID 41300830, 2025). "They showed that the fatty acid overload in hepatic cells induced an obesity-associated gene JCAD, junctional protein-associated with coronary artery disease." (PMID 34202571, 2021). "Junctional Cadherin 5 Associated (JCAD, previously known as Junctional protein associated with Coronary Artery Disease and KIAA1462) was first identified as a novel component of endothelial cell-cell junctions." (PMID 33083606, 2020). "Single nucleotide polymorphisms in the human JCAD gene associated with coronary artery disease were reported in two large-scale genetic studies." (PMID 33083606, 2020). "KIAA1462 product was also designated JCAD (Junctional protein associated with coronary artery disease), which is a novel molecular component of VE-cadherin-based endothelial cell–cell junctions, and was identified by restriction site-associated DNA (RAD) sequencing." (PMID 29883426, 2018). "In 2017, a Genome-Wide Association Study (GWAS) identified polymorphism in the gene KIAA1462, encoding the protein JCAD (Junctional protein associated with Coronary Artery Disease) as a risk for COPD." (PMID 39273437, 2024). "As a novel coronary artery disease gene, JCAD could promote atherosclerotic plaque formation via a role in the endothelial cell shear stress mechanotransduction pathway." (PMID 39080547, 2024). "Genome-wide association studies (GWAS) have consistently identified an association between coronary artery disease (CAD) and a locus on chromosome 10 containing a single gene, JCAD (formerly KIAA1462)." (PMID 31584065, 2020).
atherosclerosis (9 papers, 2018 to 2025). A disease characterized by the build-up of fatty material and calcium deposition in the arterial wall resulting in partial or complete occlusion of the arterial lumen. "JCAD has also been implicated in mechanotransduction of shear stress, as JCAD-deficient mice developed less atherosclerosis on the inner curvature of the aortic arch." (PMID 41300830, 2025). "The mechanosensor JCAD has been pinpointed in genome-wide association analyses of patients with coronary heart disease, and JCAD deficiency attenuated atherosclerosis in Apoe-knockout mice." (PMID 39507419, 2024). "We have previously demonstrated that GWAS-identified CAD risk gene JCAD/KIAA1462 regulates leukocyte adhesion and atherosclerosis in mice via regulating endothelial inflammation." (PMID 36091033, 2022). "We have now shown that loss of JCAD has a protective role in vascular function and atherosclerosis progression but is detrimental to recovery after hind limb ischaemia." (PMID 31584065, 2020). "Junctional Cadherin 5 Associated (JCAD) is an endothelial, cell-cell junction protein, and its expression is associated with cardiovascular diseases including atherosclerosis and hypertension." (PMID 33083606, 2020). "Using the STARNET data set, we identified an expression quantitative trait locus between the protective allele of the lead SNP rs2487928 which was associated with decreased expression of JCAD in both atherosclerotic and atherosclerosis free arterial tissue." (PMID 31584065, 2020). "CAD risk variants located at the JCAD (junctional cadherin 5 associated, also known as KIAA1462) locus were associated with increased gene expression in human arteries and JCAD knockout reduced the development of atherosclerosis in apolipoprotein E-deficient (ApoE−/−) mice." (PMID 37759455, 2023). "This indicates that decreased expression of JCAD associated with the rs2487928 allele is protective, leading to the hypothesis that loss of JCAD would result in reduced atherosclerosis burden." (PMID 31584065, 2020). "Our work elucidated the important role of the miR-19a-3p/JCAD pathway in endothelial cell functions, providing possible biomarkers and targets for atherosclerosis treatment." (PMID 39080547, 2024). "Although these recent studies have increased our knowledge of the possible molecular functions of JCAD, our understanding of how JCAD alters the development and progression of atherosclerosis remains limited." (PMID 31584065, 2020). "Although the function of JCAD is not completely understood, its role, especially in circulatory diseases such as hypertension and atherosclerosis, has attracted significant attention." (PMID 33083606, 2020). "In summary, our data suggest that miR-19a-3p inhibits endothelial dysfunction by targeting JCAD and may act as a protective factor in atherosclerosis." (PMID 39080547, 2024).
hepatocellular carcinoma (4 papers, 2020 to 2025). A malignant tumor that arises from hepatocytes. "JCAD polymorphisms have also been linked to pulmonary emphysema, Alzheimer’s disease, ovarian tumors, and progression of nonalcoholic steatohepatitis to hepatocellular carcinoma." (PMID 41300830, 2025). "JCAD can interact with large tumor suppressor kinase 2 (LATS2), thereby inhibiting the ability of LATS2 to phosphorylate yes-associated protein (YAP) in hepatoma cells in vitro." (PMID 41374934, 2025). "JCAD knockdown by siRNA in Huh‐7 and Huh‐7‐trans cells, the latter is a high‐metastatic hepatoma cells derived from Huh‐7 cells, resulted in down‐regulation of cyclin D1 at both mRNA and protein levels." (PMID 38509842, 2024). "One study reported high expression of JCAD in multiple hepatoma cell lines and in pre-carcinoma lesions in a mouse model of non-alcoholic steatohepatitis (NASH), as well as in human NASH-associated hepatocellular carcinoma, in contrast to the low levels of expression in normal human liver." (PMID 33083606, 2020).
endothelial dysfunction (3 papers, 2019 to 2024). In vascular diseases, endothelial dysfunction is a systemic pathological state of the endothelium (the inner lining of blood vessels) and can be broadly defined as an imbalance between vasodilating and vasoconstricting substances produced by (or acting on) the endothelium. "JCAD colocalizes with VE-cadherin in endothelial cell junctions, and JCAD deficiency may attenuate endothelial dysfunction and atherogenesis by decreasing the expression of proliferative, antiapoptotic, and proinflammatory genes." (PMID 39080547, 2024). "We have recently identified JCAD as a negative regulator of Hippo signalling in endothelial cells, suggesting that JCAD may in part contribute to endothelial dysfunction by down-regulation of Hippo signalling, leading to increased YAP activity." (PMID 31584065, 2020).
emphysema (2 papers, 2024 to 2025). "While in the WT lung, there is a marked destruction of the parenchyma causing emphysema, this elastase-induced destruction was ameliorated in the JCAD-KO lung." (PMID 39273437, 2024). "In our study, we induced inflammation and emphysema in mice via the global knockout of KIAA1462/JCAD (JCAD-KO) and confirmed it in HPMECs and A549 to examine how the loss of JCAD could affect COPD development." (PMID 39273437, 2024).
Obesity (2 papers, 2021 to 2025). Accumulation of substantial excess body fat. "The JCAD gene (formerly KIAA1462) was initially linked to extreme obesity in mammals." (PMID 41300830, 2025).
alcohol dependence (1 paper, 2021). Physical and psychological dependence on alcohol. "JCAD, KLB, and GCKR have also been associated with alcohol dependence as assessed with the AUDIT." (PMID 34135785, 2021).
Aortic dissection (1 paper, 2022). Aortic dissection refers to a tear in the intimal layer of the aorta causing a separation between the intima and the medial layers of the aorta. "We believe that it is probable that variants in the JCAD gene could decrease its expression and, in turn, generate an increase in YAP/TAZ that could produce a protective effect for the appearance of aortic dissection." (PMID 35741789, 2022).
breast carcinoma (1 paper, 2025). "Kaplan-Meier analysis of TCGA databases revealed that high JCAD expression was associated with poor prognosis in patients with breast cancer." (PMID 40860197, 2025). "In addition, the present study identified JCAD as an independent prognostic factor of breast cancer that is closely related to stage and prognosis, highlighting it as a key molecule for further study." (PMID 40860197, 2025). "Compared with control cells, JCAD-overexpressing (JCAD-OE) cells presented greater proliferation, colony formation, and EdU-positive cell ratios whereas JCAD-knockdown (JCAD-KD) cells presented the opposite trend, confirming the role of JCAD in promoting breast cancer cell proliferation." (PMID 40860197, 2025). "In addition, XAV939 can be used as a potential therapeutic approach to provide a therapeutic direction for subsequent JCAD overexpression breast cancer." (PMID 40860197, 2025). "Overall, these results suggested that JCAD activates the Wnt/β-catenin pathway by promoting an increase in downstream FZD1 expression, which mediates the EMT process and ultimately promotes breast cancer progression." (PMID 40860197, 2025). "Since JCAD, as an upstream of FZD1, is closely related to breast cancer prognosis and exosomes play a role in tumor resistance, investigating this signaling pathway and its implications for drug resistance in breast cancer is highly important." (PMID 40860197, 2025). "Although the present study did not fully elucidate the mechanisms by which JCAD regulates FZD1 and the exploration of exocrine levels is still in its infancy, the present findings provide a basis for further investigations of JCAD function in breast cancer." (PMID 40860197, 2025).
coronary atherosclerosis (1 paper, 2025). Atherosclerosis of the coronary vasculature. "Gene markers associated with coronary atherosclerosis, such as JCAD, GUCY1A3, PCSK9, and SORT1, have demonstrated significant diagnostic and prognostic value in multiple studies." (PMID 39858645, 2025).
oral cancer (1 paper, 2025). "Together, these findings highlight JCAD as a key regulator of the transition from normal to pathological vasculature and a potential therapeutic target for controlling tumor angiogenesis in oral cancer." (PMID 41374934, 2025). "Moreover, although YAP regulation downstream of JCAD has been demonstrated in previous studies, we were unable to evaluate YAP expression in either the mouse model or human oral cancer in this study, and this remains a subject for future investigation." (PMID 41374934, 2025).
tumor (4 papers, 2020 to 2026). "We tested the plasma exosomes of this batch of nude mice and, similar to in situ tumor formation model, also confirmed that JCAD expression was higher in the plasma exosomes of the JCAD-OE group." (PMID 40860197, 2025). "A role for JCAD has been identified in pathological angiogenesis with decrease vascular formation in response to matrigel and decreased tumour growth." (PMID 31584065, 2020). "Taken together, JCAD is a potential target for controlling the tumor microenvironment." (PMID 41374934, 2025). "The mRNA expression of JCAD in tumor tissues was greater than that in paracancerous tissues." (PMID 40860197, 2025). "Compared with the control, JCAD overexpression significantly promoted in situ tumor growth." (PMID 40860197, 2025). "JCAD is a potential target for controlling tumor angiogenesis mediated by TNF-α." (PMID 41374934, 2025). "Interestingly, after subcutaneously injecting tumor cells into mice, JCAD knockout (JCAD-KO) mice developed significantly smaller tumors than wild-type (WT) mice." (PMID 41374934, 2025).
cardiovascular disease (3 papers, 2013 to 2025). "Some of these compensatory mechanisms in the context of cardiovascular disease involve tissue remodeling proteins, including collagen alpha-1 (XIX) chain and junctional cadherin-associated-5 (JCAD) proteins." (PMID 41285723, 2025). "In addition to its role in cardiovascular disease, there is also evidence to suggest a role for JCAD in tumorigenesis." (PMID 33083606, 2020).
cancer (1 paper, 2025). A tumor composed of atypical neoplastic, often pleomorphic cells that invade other tissues. "Although the functional characterization of JCAD is not fully clear, its role in cancer metabolic reprogramming and Hippo signaling regulation is of particular interest." (PMID 41374934, 2025).
JCAD also shares sentences with these, for which no sentence is quoted: Alzheimer disease (2 papers); diabetes (2); myocardial infarction (2); nonalcoholic steatohepatitis (2); acute coronary syndrome (1); alcohol use disorder (1); aortic aneurysm (1); artery disease (1); ascending aortic aneurysm (1); bladder cancer (1); cervical cancer (1); cholestasis (1); chronic obstructive pulmonary disease (1); coronary stenosis (1); Hypertension (1); liver disorder (1); melanoma (1); ovarian tumors (1); type 2 diabetes mellitus (1); vascular disorder (1).